AR (androgen receptor)
Diseases named in the same sentence as AR in open-access papers (continued):
Sharing a sentence is not in itself a finding about the gene and the disease.
prostate carcinoma (continued). "The primary mechanism through which α-tocopherol influences prostate cancer progression is by reducing the concentration of the androgen receptor, which plays a key role in the development of this malignancy." (PMID 40362574, 2025). "We have reported that NCAPD3 has higher expression in prostate cancer and is involved in androgen receptor‐promoted PCa progression." (PMID 39917394, 2025). "The most direct studies of AR regulation of OXPHOS were in prostate cancer, but the effects of AR on prostate cancer OXPHOS are controversial, as some studies found AR promotes OXPHOS, whereas others found AR inhibits OXPHOS." (PMID 41216931, 2025). "For example, VNPP433-3β, a next-generation galeterone analog, was found to bind the AR and promote its degradation in prostate cancer cell lines." (PMID 40866949, 2025). "Urinary mRNAs, including those of PSMA, PCA3, and AR, play a significant role in prostate cancer development." (PMID 39859417, 2025). "The androgen receptor (AR) plays a critical role in prostate cancer, acting as a major therapeutic target due to its altered activity that contributes to tumor initiation and progression." (PMID 39960347, 2025). "Taking into consideration the strong connection between androgen-AR signaling and prostate cancers, some of the available options for treatments are based on the application of androgen deprivation therapy (ADT) or direct targeting by anti-androgens." (PMID 40747210, 2025). "FLII homolog inhibits androgen receptor signaling, slowing prostate cancer development, while FLII itself inhibits selective autophagy and promotes breast cancer growth by blocking p62‐mediated recognition of LC3." (PMID 39964147, 2025). "Consistent with the findings in AR-independent mouse prostate cancers, AR-negative human prostate cancers exhibited lower levels of DNA methylation compared to AR-positive counterparts." (PMID 39743630, 2025). "We next considered how each class of FOXA1 alteration associated with outcomes based on the first instance of prostate cancer systemic treatment by first-line ADT, second-generation AR signaling inhibitors (ARSI), and taxane chemotherapies." (PMID 39745364, 2025). "AR level was significantly reduced when C4-2B prostate cancer cells were treated with different concentrations of Myc inhibitor 10058-F4." (PMID 40044981, 2025). "The regulation of AR on prostate cancer, and the blocking of AR signaling pathway by AR antagonists and sterogenic enzyme inhibitors have been widely studied." (PMID 41347146, 2025). "Deletion of LKB1 promoted AR-independent lineage transformation, as well as global DNA hypomethylation in prostate cancer." (PMID 39743630, 2025). "The androgen receptor (AR) signaling pathway is central to prostate cancer progression and treatment, particularly in the context of androgen deprivation therapy." (PMID 40940870, 2025). "In summary, our results indicate that overexpression of HIC1 decreases AR expression, leading to reduced growth, proliferation, and metastatic potential of prostate cancer cells." (PMID 41050263, 2025). "Prostate cancer (PCa) is a common tumour among men globally, with androgen receptor (AR) signalling playing a pivotal role in its pathogenesis." (PMID 39763034, 2025). "Eugine Lee's research discovered a small molecule inhibitor (C3) of nuclear β‐catenin activity that inhibits the growth of prostate cancer cells by blocking the interaction between β‐catenin/T‐cell factor and β‐catenin/AR protein." (PMID 39964832, 2025). "In prostate cancer models, these alkaloids suppress 5-α-reductase activity and downregulate androgen receptor expression through modulation of the PI3K/AKT signaling pathway." (PMID 41154606, 2025). "While mainstream perspectives suggest that the synergy between YAP and AR promotes the development of prostate cancer, a recent study presents a contrasting viewpoint." (PMID 39963114, 2025).
prostate carcinoma (continued). "The limitation of BAT is that AR expression is required, and only AR-positive prostate cancers are responsive." (PMID 41264145, 2025). "AR degradation emerges as a promising therapeutic strategy to combat aggressive prostate cancer, especially to overcome drug-resistance." (PMID 41020902, 2025). "Androgen deprivation therapy (ADT) and androgen receptor (AR) signaling inhibitors (ARSIs) are the primary systemic treatment for patients with advanced prostate cancer." (PMID 41304997, 2025). "AR-driven prostate cancer models are preferentially sensitive to BRD4 inhibition, since BRD4 and AR co-localise at target loci, including super-enhancers, to drive AR-mediated gene transcription." (PMID 40163908, 2025). "This review offers a novel perspective on prostate cancer research by exploring the interactions and related mechanisms between AR and YAP in this context." (PMID 39963114, 2025). "In vitro experiments on prostate cancer cell lines (e.g., LNCaP, PC-3) will verify the regulatory effects on AR signaling pathways, assessing PSA expression, cell processes, and using siRNA to distinguish interactions." (PMID 40331986, 2025). "Rationale: Prostate cancer (PCa) growth is facilitated by the androgen receptor (AR) and its downstream signaling pathways, making AR-targeted therapy crucial for treating advanced stages." (PMID 40365288, 2025). "ERG and other ETS family transcription factors are over-expressed in half of human prostate cancers as a result of fusions with the promoter sequence of the androgen receptor (AR)-dependent TMPRSS2 gene." (PMID 40332161, 2025). "Our comprehensive study on the AR/IRS2/PI3K/AKT axis also provides theoretical support for the development of more effective treatment strategies for prostate cancer." (PMID 41050263, 2025). "In advanced prostate cancer (PC), in particular after acquisition of resistance to androgen receptor (AR) signaling inhibitors (ARSI), upregulation of AR splice variants compromises endocrine therapy efficiency." (PMID 39258426, 2025). "We then examined GR expression in prostate cancer cell lines and found that as the disease progressed, GR expression gradually increased, whereas AR expression decreased." (PMID 40759641, 2025). "In prostate cancer, androgen receptor (AR) signaling has been shown to downregulate MHC class I (HLA) expression, thereby reducing tumor immunogenicity, a process that is reversed by AR inhibition." (PMID 40565184, 2025). "ET516 destroys AR condensates, effectively inhibits AR transcriptional activity, and suppresses the proliferation and tumor growth of prostate cancer cells expressing AR resistant mutants." (PMID 40231263, 2025). "Consistent with previous studies, we observed that AR-independent prostate cancer was enriched with basal, metastasis and stemness signatures." (PMID 39743630, 2025). "Basal-like tumors are enriched in the basal lineage CD49f signature, while luminal markers such as NKX3.1, KRT18, and AR are elevated in luminal-like tumors, supporting the link between subtypes and the established prostate cancer biology." (PMID 40867349, 2025). "The AR functions as a transcription factor (TF) that regulates genes essential for prostate cancer cell proliferation and survival." (PMID 39858458, 2025). "CNPY2 has also been found to play a role in prostate cancer progression through its modulation of the androgen receptor (AR)." (PMID 40001982, 2025). "AR antagonists are important therapeutics that inactivate the AR and are used clinically in prostate cancer hormone therapy." (PMID 40072554, 2025). "Androgen receptor (AR) signaling is a central driver of both prostate development and prostate cancer pathogenesis." (PMID 40643528, 2025). "have found that combination of rapamycin and bicalutamide (anti-androgenic drug) improved anti-prostate cancer effect due to the suppression of mTOR stimulated AR transcriptional activity." (PMID 39917165, 2025).
prostate carcinoma (continued). "Regulating the signaling pathway AR‐Akt‐HK2 was the primary mechanism by which wogonin's anticancer effect on prostate cancer was mediated." (PMID 41164269, 2025). "They demonstrated that androgen stimulation-induced AR activation in prostate cancer cells significantly reduced Ser-127 phosphorylation and increased both nuclear and total cellular YAP protein levels, thereby promoting the expression of YAP-dependent genes." (PMID 39963114, 2025). "This real‐world study demonstrates that AR monitoring via liquid biopsy predicts treatment response and progression in metastatic castration‐resistant prostate cancer." (PMID 40558023, 2025). "PPARG (Peroxisome proliferator-activated receptor gamma), a member of the nuclear receptor superfamily, has demonstrated bidirectional crosstalk with AR signaling pathways in human prostate cancer." (PMID 40458476, 2025). "In estrogen receptor (ER)-positive breast cancer cells and androgen receptor (AR)-positive prostate cancer cells, the sex hormone signaling pathways induce ANG-mediated cleavage of aminoacylated mature tRNAs, leading to abundant accumulations of tRNA halves." (PMID 40471969, 2025). "Treatment and monitoring of prostate cancer (PC) patients is primarily based on the androgen receptor (AR) signaling pathway." (PMID 40181402, 2025). "Since prostate cancer is an androgen-dependent cancer, the majority of first-line treatments concentrate on suppressing androgen synthesis and the androgen receptor (AR) signaling axis." (PMID 39996908, 2025). "For instance, the PI3K pathway promotes progression to castration-resistant prostate cancer following androgen deprivation therapy via interactions with the androgen receptor pathway." (PMID 40713830, 2025). "Understanding these AR mechanisms is crucial for developing targeted therapies and improving patient outcomes in prostate cancer." (PMID 40940870, 2025). "Androgen receptor signaling drives prostate cancer progression, making androgen deprivation therapy (ADT) the foundation of treatment for metastatic disease." (PMID 41150771, 2025). "For example, prostate cancer-specific therapies (androgen receptor-targeted therapy) have effects on the gastrointestinal microbiota." (PMID 41278192, 2025). "Recent evidence suggests that HOXB13 plays critical AR-independent functions in repressing lipogenic programs and promoting prostate cancer (PCa) metastasis." (PMID 41277556, 2025). "In this network, the AR emerged as a central node, underscoring its critical role in regulating key pathways involved in prostate cancer progression." (PMID 39980567, 2025). "The primary target for prostate cancer treatment is androgen receptor (AR); however, resistance to AR signaling-targeted therapies remains a significant challenge in the treatment of advanced prostate cancer." (PMID 40115748, 2025). "Advanced prostate cancer is invariably fatal, with the androgen receptor (AR) being a major therapeutic target." (PMID 39787247, 2025). "Although tetracyclines are not traditionally classified as antiandrogens, they have been observed to affect AR expression and transcriptional activity, particularly in prostate cancer models." (PMID 40284400, 2025). "The growth of prostate tumours is driven by androgen receptor (AR) signalling and initial therapeutic options for advanced prostate cancer are hormone‐based therapies such as anti‐androgens." (PMID 40387385, 2025). "Prostate cancer originates from secretory prostate epithelial cells, where AR, a transcription factor regulated by androgen, plays a key role in driving the differentiation." (PMID 40511682, 2025). "The androgen receptor is a protein that allows cells to respond to these hormones and is well known in prostate cancer, but its role in bladder cancer has been unclear." (PMID 41463239, 2025). "MDM2 is known to mediate the ubiquitination and degradation of AR, where MDM2 knockout results in increased AR expression in prostate cancer cells." (PMID 39960347, 2025).
prostate carcinoma (continued). "Compared to AR-positive cancer cells, AR-negative/-low prostate cancer cells were more sensitive to Bobcat339 treatment." (PMID 39743630, 2025). "FOXA1 and FOXA2, members of this family, are known to interact with AR to regulate transcriptional programs in prostate cancer." (PMID 40898340, 2025). "It has been demonstrated that both in the normal prostate gland and prostate cancer, activation of the androgen receptor (AR) promotes prostate growth." (PMID 41516250, 2025). "Androgen receptor (AR), a nuclear transcription factor in the steroid hormone receptor family, is central to prostate cancer pathogenesis." (PMID 39917165, 2025). "Androgen receptor (AR) activity is a key component in the pathophysiology of prostate cancer and is a regulator of the transcription of genes necessary for cell cycle progression from the G1 to S phase." (PMID 40075623, 2025). "Sintokamide A (SINT1), a small peptide isolated from the marine sponge Dysidea species, has been shown to selectively suppress AR activity in LNCaP prostate cancer cells by inhibiting transactivation of the AR NTD, specifically targeting the AF-1 region." (PMID 41020902, 2025). "The androgen receptor (AR) serves as a critical driver in the pathogenesis and progression of prostate cancer (PCa)." (PMID 40552308, 2025). "Androgen receptor (AR) signaling has an important role in the development and progression of prostate cancer." (PMID 40003074, 2025). "In redifferentiation, NE prostate cancer also eventually loses AR expression, entirely relying on alternate pathways for proliferation." (PMID 39941808, 2025). "YAP-mediated tumor-suppressive effects are also detected in resistant models like androgen receptor (AR) in prostate cancer." (PMID 40673277, 2025). "As a result, considerable attention in prostate cancer research has been directed toward inhibiting AR signaling to mitigate the development of CRPC." (PMID 39976818, 2025). "In prostate cancer, samuraciclib inhibited cell and tumour growth by targeting proliferative pathways and AR signalling and inducing apoptosis." (PMID 40163908, 2025). "Cell secretome studies corroborated that PGC1α-dependent ERRα regulation in prostate cancer cells suppresses the growth of tumor cells exposed to their conditioned media, independently of androgen receptor status." (PMID 40268923, 2025). "Androgen receptor (AR) splice variants (AR-Vs) have emerged as potential resistance mechanisms to AR-targeted agents (ARTAs) in prostate cancer (PC), particularly in the context of castration-resistant disease." (PMID 40859365, 2025). "Here we identify p300/CBP-mediated multisite histone H2B N-terminal acetylation (H2BNTac) as a defining feature of oncogenic enhanceosomes in androgen receptor (AR)-positive prostate cancer." (PMID 41044247, 2025). "Preclinical results were promising—ARV-110 effectively degraded AR in several cell lines of prostate cancer and significantly reduced tumour size in mouse models." (PMID 40430296, 2025). "While androgen deprivation therapy (ADT) remains the mainstay of systemic treatment, the addition of AR signaling inhibitors (ARSIs) provides substantial improvement in overall survival and quality of life for many men with advanced prostate cancer." (PMID 39859392, 2025). "The following section summarizes key natural products that have been shown to promote AR degradation in prostate cancer cells." (PMID 41020902, 2025). "Prostate cancer (PCa) tumor growth and progression are largely dependent on deregulated androgen receptor (AR) function at initial diagnosis (1, –3)." (PMID 41231955, 2025). "Another recent report demonstrates that the tumor suppressor gene LBK1 (STK11) is lost in AR-independent prostate cancer subtypes." (PMID 40454483, 2025). "Further analysis in cell culture and xenograft models demonstrated that GGT6 expression was modulated at the transcription level by AR signal activity in prostate cancer." (PMID 40094020, 2025).
prostate carcinoma (continued). "The advent of AR inhibitor apalutamide has extended the survival period for patients with advanced prostate cancer." (PMID 40458791, 2025). "Advanced prostate cancer is generally treated with the pharmacological inhibition of androgen receptor (AR) signaling." (PMID 40869121, 2025). "Several other lncRNAs, including PCAT1, PCAT19, PCA3, and PCGEM1, have also been reported to play important biological roles in PCa by regulating prostate cancer cell proliferation, metastasis and also by modulating AR expression." (PMID 40124994, 2025). "Targeting androgen biosynthesis and androgen receptor (AR) function remains the cornerstone of treatment for prostate cancer (PCa) patients who have progressed beyond surgery and/or radiation therapies." (PMID 40832297, 2025). "As a cancer-promoting factor, the abnormal expression of the AR in malignant tumors such as prostate cancer and gastric cancer can promote tumor growth and induce drug resistance in tumor cells." (PMID 40729027, 2025). "p300/CBP bromodomain inhibitor CCS1477 is currently in early-phase clinical trials; thus, we tested the efficacy of CCS1477 and another bromodomain inhibitor, GNE-049, in AR-positive prostate cancer cells." (PMID 41044247, 2025). "Alterations in the androgen receptor (AR) have been shown to play a role in prostate cancer development." (PMID 40002150, 2025). "For instance, androgen receptor (AR) degraders have demonstrated potential in overcoming resistance to the AR antagonist enzalutamide during prostate cancer treatment." (PMID 39898116, 2025). "One of the most common mechanisms of resistance developed by prostate cancer cells in response to castrate conditions is an increase in AR protein expression." (PMID 40002188, 2025). "In turn, TET2 is inhibited by AR in prostate cancer cells through two pathways: AR‐induced inhibition of TET2 expression by the miR‐29 family, and direct binding of AR to the enhancer region of TET2 and inhibition of its transcription." (PMID 40599235, 2025). "Owing to its central involvement in prostate cancer development and progression, the AR signaling pathway is a critical therapeutic target." (PMID 41020902, 2025). "Isosilybin B promotes AR degradation in prostate cancer cells by disrupting the PI3K-Akt-Mdm2 signaling pathway." (PMID 41020902, 2025). "The AR is a critical transcription factor that plays a key role in driving the malignant progression of prostate cancer." (PMID 41050263, 2025). "A group of lncRNAs found to be upregulated in prostate cancer patients through RNA‐Seq analysis were subsequently examined for their interactions with several proteins targeted by the androgen receptor." (PMID 40556338, 2025). "Supporting evidence from prostate cancer shows that AR can upregulate EMT-related transcription factors, including Twist-related protein 1 (TWIST1) and zinc finger protein SNAI1 (SNAI1)." (PMID 40940929, 2025). "Blocking this ROS upregulation using apocynin or androgen receptor antagonists enhances the sensitivity of prostate cancer cells to radiotherapy." (PMID 40178629, 2025). "We effectively knocked down AR expression at both the mRNA as well as protein levels in vitro in AR-expressing prostate cancer cell lines." (PMID 40115963, 2025). "The central positioning of AR within this pathway network highlights its pivotal role in prostate cancer biology, particularly in androgen-dependent signaling." (PMID 39980567, 2025). "Nimbolide, a limonoid found in neem leaves and flowers, has demonstrated potent effects against prostate cancer, primarily through targeting androgen receptor signalling, generating reactive oxygen species (ROS), and inducing cell cycle arrest and DNA damage." (PMID 41294806, 2025). "The Wnt/β-catenin signaling pathway is considered a key pro-cancer signal in prostate cancer that can interact synergistically with AR signaling to promote tumor cell proliferation and metastasis." (PMID 40008000, 2025).